NSD2 (nuclear receptor binding SET domain protein 2)
Diseases named in the same sentence as NSD2 in open-access papers (continued):
Sharing a sentence is not in itself a finding about the gene and the disease.
Sotos syndrome (4 papers, 2014 to 2024). Sotos syndrome is a rare multisystemic genetic disorder characterized by a typical facial appearance, overgrowth of the body in early life with macrocephaly, and mild to severe intellectual disability. "Because of their high sequence similarities with NSD1, both the NSD2 and NSD3 genes were tested previously as potential candidates for NSD1-negative Sotos syndrome cases." (PMID 27834868, 2016).
cervical cancer (3 papers, 2020 to 2025). A primary or metastatic malignant neoplasm involving the cervix. "NSD2 knockout suppresses metastasis in cervical cancer by inhibiting TGF‐β/TGF‐βRI/SMAD signaling." (PMID 38400589, 2025). "Moreover, NSD2 inhibition suppressed cervical cancer tumorigenesis and metastasis, and reduced expressions of transforming growth factor-β1 (TGF-β1) and its receptor TGF-βRI." (PMID 34671018, 2021).
diabetic nephropathy (3 papers, 2022 to 2025). "Nonetheless, YTHDF1 has also been reported to play a role in mitigating renal interstitial fibrosis induced by diabetic nephropathy by enhancing the stability of nuclear receptor-binding SET domain protein 2 (NSD2) through METTL3-mediated m6A modification." (PMID 39756462, 2025). "Recently, the M6A modification of NSD2 has been found to be involved in the regulation of renal interstitial fibrosis in diabetic nephropathy." (PMID 37865763, 2023). "Overexpression of NSD2 not only alleviates interstitial fibrosis in kidney tissue of mice with diabetic nephropathy, but also reduces fibrosis-related markers in HG-treated SV40-MES-13 cells." (PMID 37865763, 2023). "The M6A modification of NSD2 may become an effective target for the treatment of diabetic nephropathy in the future." (PMID 37865763, 2023). "This study focused on the role of NSD2 in the renal impairment during diabetic nephropathy (DN)." (PMID 35354439, 2022). "This study showed that METTL3 in mesangial cells can improve their mRNA stability by promoting NSD2 M6A modification with the participation of YTHDF1, reducing interstitial fibrosis and alleviating the progression of diabetic nephropathy." (PMID 37865763, 2023).
glioma (3 papers, 2016 to 2020). A benign or malignant brain and spinal cord tumor that arises from glial cells (astrocytes, oligodendrocytes, ependymal cells). "NSD2 is overexpressed in many cancer types: breast, glioma and prostate and is generally related to poor prognosis." (PMID 32153656, 2020). "NSD1 has been implicated in cancers of the brain such as glioma and neuroblastoma and there has been extensive work done on characterization of the NSD family including crystal structures for each of NSD1 / NSD2 and NSD3." (PMID 26781748, 2016).
metastatic prostate carcinoma (3 papers, 2018 to 2023). A carcinoma that arises from the prostate gland and has spread to other anatomic sites. "Taken together, these observations demonstrate that increased expression of NSD2 is associated with lethal and metastatic prostate cancer, and establish the functional relevance of NSD2 for metastatic prostate cancer progression." (PMID 30518758, 2018). "NSD2 is also highly expressed in metastatic prostate cancer, where its repression can inhibit metastasis, so that NSD2 has been proposed as a key driver of the tumor, and therefore, as a critical therapeutic target for this disease." (PMID 36232375, 2022).
neuroblastoma (3 papers, 2016 to 2022). Neuroblastoma (NB) is the most common solid, extracranial childhood tumor. "NSD2 is emerging as critical target that controls maintenance of leukemic cell and neuroblastoma cell differentiation." (PMID 32826945, 2020). "It was similar that neuroblastoma cell differentiation decreased NSD2 level through proteosomal degradation." (PMID 32826945, 2020).
triple-negative breast carcinoma (3 papers, 2020 to 2025). An invasive breast carcinoma which is negative for expression of estrogen receptor (ER), progesterone receptor (PR), and human epidermal growth factor receptor 2 (HER2). "Notably, EZH2 and NSD2 expression were coordinately higher in triple-negative breast cancer (TNBC) than that in other subtypes." (PMID 33665162, 2020).
viral infection (3 papers, 2015 to 2021). "Our result indicated that the expression level of the +nsd-2 gene encoding the putative receptor for BmBDV was significantly decreased by virus infection." (PMID 33801623, 2021). "We examined the expression level of genes encoding other transporters in the midgut after virus infection to investigate whether the decrease in expression levels caused by virus propagation is exhibited only by the +nsd-2 gene." (PMID 33801623, 2021). "We further investigated the function of NSD2 in IFN-I production in response to viral infection." (PMID 34315861, 2021). "However, only the +nsd-2 gene expression level decreased with virus infection." (PMID 33801623, 2021).
adenoma (2 papers, 2013 to 2022). A neoplasm arising from the epithelium. "Quantitative analysis of microarray data confirmed that these methyltransferases, which included Setd3, Setd5, Suv39h2, Smyd3, Prmt3, Prmt6, Nsd1, and Nsd2 were up-regulated in metastases compared to adenomas, carcinomas, or disseminated cells." (PMID 23520493, 2013).
breast tumor (2 papers, 2025). "We further examined NSD2 and H3K36me2 expression in 114 independent primary breast tumor tissues and 20 adjacent normal tissues by immunohistochemistry analysis." (PMID 40097917, 2025). "It was observed that the inclusion of NSD2 exon 2 was significantly elevated in our collected breast tumors compared with the counterparts." (PMID 39667501, 2025). "According to the TCGA-BRCA dataset, the inclusion of NSD2 exon 2 was significantly elevated in the breast tumors compared with normal tissues." (PMID 39667501, 2025). "We detected the status of NSD2 exon 2 in 15 ER + breast tumors and matched normal tissues." (PMID 39667501, 2025).
cardiac hypertrophy (2 papers, 2019 to 2023). "The activation of angiogenic key factors in NSD2‐dependent tumour progression may play the same role in myocardial growth and angiogenesis during cardiac hypertrophy." (PMID 30334333, 2019). "In addition, a mouse model of cardiac hypertrophy with concurrent conditional knockdown of Nsd2 in the myocardium resulted in a milder ventricular remodeling phenotype and improved cardiac function, attributed to reduced H3K36me2, thus demonstrating a role for NSD2 in ventricular remodeling." (PMID 37504561, 2023). "Moreover, NSD2 expression was significantly up‐regulated under cardiac hypertrophy." (PMID 30334333, 2019). "Taken together, ventricular remodelling model was successfully constructed based on the pathological aspects of cardiac hypertrophy and fibrosis, and HKM and NSD2 are involved in the pathological process of ventricular remodelling." (PMID 30334333, 2019).
chondroblastoma (2 papers, 2019 to 2022). A benign, chondroid-producing, well-circumscribed, lytic neoplasm usually arising from the epiphysis of long bones. "Similarly to H3K27M mutations, H3.3K36M expression in chondroblastoma correlates with global reduction in H3K36 methylation, due to inhibition of NSD2/MMSET, a methyltransferase that catalyzes mono- and di-methylation of H3K36, and SETD2, which catalyzes trimethylation of H3K36me2." (PMID 30654820, 2019).
colorectal tumors (2 papers, 2022 to 2025). "Our results showed that knockout of NSD2 inhibited the expression of Ki67 and CD31 in colorectal tumor tissues, suggesting that overexpression of NSD2 can promote the proliferation and angiogenesis of colorectal tumors." (PMID 38400589, 2025).
congenital heart disease (2 papers, 2023). A heart disease that is present at birth. "Finally, variants in NSD2 have been associated with congenital heart disease; in fact, both loss-of-function (LoF) and gain-of-function (GoF) variants in NSD2 have been associated with abnormal heart morphology linked to disrupted cardiac patterning." (PMID 37504561, 2023). "Variants in the genes that encode the H3K36 methyltransferases, NSD1, NSD2, and, ASH1L, have been linked to congenital heart disease." (PMID 37504562, 2023). "NSD2 (HGNC previous symbol: WHSC1) lies in the critical deletion region of Wolf–Hirschhorn syndrome (WHS; OMIM #194190), a neurodevelopmental disorder marked by facial dysmorphology and growth retardation, of which a subset of patients presented with congenital heart disease." (PMID 37504561, 2023).
diabetes (2 papers, 2021 to 2022). "More relevantly, NSD2 has been demonstrated to be downregulated in patients with diabetes mellitus, and its upregulation increased insulin secretion and reduced glucose concentration through promoting pancreatic β cell proliferation." (PMID 35354439, 2022). "Interestingly, NSD2 has been demonstrated to be downregulated in patients with type 2 diabetes mellitus, and NSD2 upregulation promoted the proliferation of pancreatic β cells and increased insulin secretion, leading to reduced glucose concentration." (PMID 35354439, 2022). "Moreover, NSD2-mediated H3K36 methylation has been reported to play a significant role in adipose tissue development, and NSD2 deletion was suggested to lead to lipodystrophy, which is correlated with hyperlipidemia, insulin resistance, and diabetes." (PMID 35354439, 2022).
esophageal SCC (2 papers, 2019 to 2024). "Over-expression of SMYD2 and NSD2 was also noticed in various cancers, for instance, esophageal squamous cell carcinoma, pediatric lymphoblastic leukemia, colon and skin cancers." (PMID 31160694, 2019).
glomerulosclerosis (2 papers, 2022). A hardening of the kidney glomerulus caused by scarring of the blood vessels. "In vivo, overexpression of NSD2 alleviated the renal impairment and the pathological changes, including glomerular dilatation, glomerulosclerosis, diffuse mesangial proliferation, and fibrosis in mice and reduced the expression of interstitial fibrosis-related markers in tissues." (PMID 35354439, 2022).
Insulin resistance (2 papers, 2022 to 2024). Increased resistance towards insulin, that is, diminished effectiveness of insulin in reducing blood glucose levels. "Additionally, results from the glucose tolerance test (GTT) and insulin tolerance test (ITT) indicated that intestine‐specific NSD2 knockout ameliorated HFCD‐induced glucose intolerance and insulin resistance." (PMID 38923875, 2024).
laryngeal carcinoma (2 papers, 2017 to 2022). Carcinoma that arises from the laryngeal epithelium. "NSD1- or histone H3-mutated tumors have been found to constitute a hypomethylated subset within HPVneg HNSCC while NSD1 and NSD2 mutations have been associated with favorable prognosis in laryngeal cancers." (PMID 35664801, 2022). "Subsequent validation in an independent set of 63 laryngeal cancer samples again demonstrated that mutations in NSD1 or NSD2 are independent favorable prognostic biomarkers for laryngeal cancer." (PMID 29176703, 2017). "Altogether, these observations that indicated loss-of-function mutations in NSD1 or NSD2 are associated with better prognosis specifically in laryngeal cancer." (PMID 29176703, 2017). "Although most common laryngeal gene mutations are found in both subclasses, better prognosis is strongly associated with damaging mutations of the methyltransferases NSD1 and NSD2, with findings confirmed in an independent validation cohort consisting of 63 laryngeal cancer patients." (PMID 29176703, 2017). "This analysis identified two distinct clusters of laryngeal cancer, associated with strong prognostic value, and showed that mutations in the genes NSD1 and NSD2 entirely segregated to the cluster with favorable prognosis." (PMID 29176703, 2017). "In sum, this work nominates NSD1 and NSD2 as rapidly exploitable prognostic biomarkers and targets for functional scrutiny in laryngeal cancers." (PMID 29176703, 2017).
melanoma (2 papers, 2012 to 2025). A malignant, usually aggressive tumor composed of atypical, neoplastic melanocytes. "Furthermore, our study highlights the role of three specific miRNAs (miR‐23a, miR‐24, and miR‐31) as mediators of NSD2 downregulation, suggesting a regulatory mechanism underlying melanoma cell plasticity." (PMID 40386826, 2025). "This figure illustrates the proposed mechanism of NSD2 regulation in melanoma following romidepsin and interferon‐α2b (RI) treatment." (PMID 40386826, 2025). "We investigated the role of Nuclear Receptor Binding SET Domain Protein 2 (NSD2) and microRNAs (miRNAs) in melanoma de‐differentiation following Romidepsin and Interferon‐α2b (RI) treatment." (PMID 40386826, 2025). "RI induces a de‐differentiation process, particularly in proliferative melanoma cells, leading to NSD2 downregulation." (PMID 40386826, 2025). "RT‐qPCR analysis confirmed that NSD2 expression was significantly downregulated after RI treatment, specifically in proliferative melanoma cell lines." (PMID 40386826, 2025). "RI treatment led to the downregulation of CCND1, MYC, and BCL2 in proliferative cell lines, further supporting the role of NSD2 in melanoma progression." (PMID 40386826, 2025). "This study aims to explore the role of NSD2 and miRNAs in melanoma's response to the RI." (PMID 40386826, 2025). "Given the critical role of NSD2 in melanoma progression, therapeutic strategies targeting NSD2 expression or activity—including miRNA‐based therapies or small‐molecule inhibitors—may offer new avenues for improving treatment outcomes." (PMID 40386826, 2025). "Additionally, we identified specific miRNAs as mediators of NSD2 downregulation, influencing melanoma cell viability and fitness." (PMID 40386826, 2025). "Notably, miR‐23a and miR‐24 exhibited a significant anti‐correlation with NSD2 expression, while miR‐31 demonstrated a non‐significant anti‐correlation, possibly due to its low expression in human melanoma cells." (PMID 40386826, 2025). "While NSD2 is a well‐established oncogene, its role in melanoma has not been previously characterized." (PMID 40386826, 2025).
myelogenous leukemia (2 papers, 2020 to 2024). "Although the specific E3 ligase responsive to phosphorylation of NSD2 in MM remains unidentified, breast cancer 1 (BRCA1) was found to act as an E3 ligase to support NSD2 degradation in the human myelogenous leukemia cell line K56298." (PMID 39394462, 2024). "Here, we uncovered NSD2 as an innate erythroid differentiation-related factor through a genome-wide CRISPR library screen and explored the regulatory role of NSD2 during myeloid leukemia cell differentiation." (PMID 32826945, 2020).
Obesity (2 papers, 2021 to 2024). Accumulation of substantial excess body fat. "This may reveal potential targets for therapeutic interventions relevant not only to patients with NSD2 deficiency, but also potentially even to patients with obesity in general." (PMID 33941880, 2021). "Additionally, a notable increase in H3K36me2 levels was noted in the colons of both obese and HFCD‐fed mice, suggesting activation of the intestinal NSD2–H3K36me2 axis is activated during obesity, which may play a role in NASH progression." (PMID 38923875, 2024).
osteoporosis (2 papers, 2022 to 2025). A condition of reduced bone mass, with decreased cortical thickness and a decrease in the number and size of the trabeculae of cancellous bone (but normal chemical composition), resulting in increased fracture incidence. "Subcutaneous melatonin (10 mg/kg, twice weekly) alleviated osteoporosis in aged mice by upregulating nuclear receptor‐binding SET domain protein 2 (NSD2)." (PMID 40452254, 2025). "In clinic, severity of senile osteoporosis (SOP) was negatively correlated with melatonin level in bone marrow, as well as NSD2 expression in BMSCs." (PMID 35220680, 2022).
pancreatic cancer (2 papers, 2023 to 2024). "Our results showed that NSD2 acted as a novel tumor suppressor in pancreatic cancer and revealed the multiple mechanisms by which NSD2 suppresses both p65 phosphorylation and downstream transcriptional activity during pancreatic tumorigenesis." (PMID 38889281, 2024). "Notably, when compared with NSD1 and NSD2, we find that NSD3 is prominently expressed, and its expression is significantly linked with clinical outcome in pancreatic cancer." (PMID 37062069, 2023).
rectal cancer (2 papers, 2021 to 2025). A primary or metastatic malignant neoplasm that affects the rectum. "In addition, NSD2 mRNA upregulation was detected in the rectal cancer tissues (n = 92), whereas relative low expression was detected in normal rectal tissues (n = 318)." (PMID 34671018, 2021).
benign prostatic hyperplasia (1 paper, 2023). A non-cancerous nodular enlargement of the prostate gland. "Immunohistochemistry was performed to evaluate the expression pattern of NSD2 in 34 cases of benign prostatic hyperplasia (BPH), 36 cases of prostatic intraepithelial neoplasia (PIN), and 57 cases of PCa, including 19 cases of metastatic castration-resistant prostatic cancer (mCRPC)." (PMID 38062230, 2023).
bladder tumors (1 paper, 2022). "It has been reported that, upon NSD2 knockout, zebrafish presented developmental defects resembling Wolf–Hirschhorn Syndrome; however, at later stages, these animals developed swim bladder tumors, indicating a potential tumor suppressor function of NSD2." (PMID 36232375, 2022).
brain tumors (1 paper, 2022). "Set2 homologs, including NSD1, NSD2, NSD3, and SETD2, are frequently mutated, translocated, or amplified in a variety of human cancers, and oncohistone mutations that dysregulate H3K36 methylation cause pediatric brain tumors." (PMID 35263330, 2022).
cardiomyopathy (1 paper, 2025). A disease of the heart muscle or myocardium proper. "The cardiomyopathy-associated targets were Dnmt1, Hdac1, Dot1l, Setd5, Nsd2, Usp3, Bap1, Prkca, Prkcb, Crebbp and Clock: 11 out of 81 (13.6% of total targets)." (PMID 40076868, 2025).
chondrosarcoma (1 paper, 2021). A malignant cartilaginous matrix-producing mesenchymal neoplasm arising from the bone and soft tissue. "Another mutation affecting a modification hotspot of histone H3 is the H3K36M mutation in chondrosarcoma which impairs K36 modifications by inhibition of the H3 lysine 36-specific histone methyltransferases Nuclear Receptor Binding SET Domain Protein 2 (NSD2) and SET domain containing 2 (SETD2)." (PMID 33568205, 2021).
colitis (1 paper, 2024). Inflammation of the colon. "Given that NSD2 loss in IECs led to a lower FMO‐mediated taurine concentration, we next investigated whether supplementation of taurine could alleviate experimental colitis caused by NSD2 deficiency." (PMID 39658533, 2024).
colon adenocarcinoma (1 paper, 2022). "We revealed the colon adenocarcinoma patients (COAD) with mutations of a CRs set (EP300, MSH6, NSD2 and TRRAP) mediate a better survival with low expression of MAP2 and could benefit from taxnes." (PMID 36180906, 2022).
erythroleukemia (1 paper, 2022). Acute erythroid leukemia characterised by the presence of at least 50% erythroid precursors and at least 20% myeloblasts in the bone marrow. "Thus, the interaction between NSD2 and BRCA1 could become a target mechanism to establish new therapies for erythroleukemia." (PMID 36232375, 2022).
Hepatic steatosis (1 paper, 2024). Steatosis is a term used to denote lipid accumulation within hepatocytes. "Thus, our data support the notion that intestine‐specific NSD2 knockout protects mice from HFCD‐induced hepatic steatosis and inflammation." (PMID 38923875, 2024).
laryngeal tumors (1 paper, 2017). "The results were specific to mutation rather than altered gene expression, as among cases with NSD1 and NSD2 wild-type alleles in oropharynx and hypopharynx tumors and laryngeal tumors, NSD1 mRNA expression levels did not predict survival." (PMID 29176703, 2017).